VWF (von Willebrand factor)
Diseases named in the same sentence as VWF in open-access papers (continued):
Sharing a sentence is not in itself a finding about the gene and the disease.
COVID-19 (continued). "For example, the acute-phase protein von Willebrand factor (VWF) is highly up-regulated in severe COVID-19, concomitant with reduced activity of the protease ADAMTS13, which cleaves VWF following its secretion from endothelial cells or platelets, thereby reducing its prothrombotic potential." (PMID 40692561, 2025). "Rare variation in the VWF locus may thus be a relevant subject of research toward deciphering host genetic factors contributing to endothelial damage in COVID-19 patients." (PMID 41585277, 2025). "Cluster M3 was highly correlated to cluster M4 as indicated by a high Pearson correlation coefficient (r = 0.92) between the 2 clusters, and contains proteins with a similar alteration in COVID-19 cohorts (eg, VWF, leucine-rich α2-glycoprotein 1, galectin-1, and polymeric immunoglobulin receptor)." (PMID 40224277, 2025). "Hence, our results neither support nor provide a causal explanation for the genetic mechanisms underlying dysregulated levels of VWF, FVIII or ADAMTS13 in COVID-19 severe patients." (PMID 41585277, 2025). "Although many non-coding variants in ABO are associated with VWF levels, VTE risk, and COVID-19 severity, the mechanisms underlying these associations remain unclear." (PMID 41311061, 2025). "The significant increase in vWF levels observed in individuals with COVID-19 signifies endothelial damage or impairment, promoting platelet aggregation at the site of injury and potentially leading to hyperactivation of the coagulation pathway, thereby initiating thrombotic events." (PMID 40821797, 2025). "In this prospective monocentric observational study, we investigated whether COVID-19-associated coagulopathy meets the criteria for TMA and evaluated the roles of complement activation and vWF/ADAMTS13 imbalance in disease severity." (PMID 40508203, 2025). "The demonstration of both activated pathways, even in the absence of signs of TMA, could enhance the hypothesis that the complement activation and vWF/ADAMTS13 axis both contribute to the pathogenesis of COVID-19 coagulopathy." (PMID 40508203, 2025). "Furthermore, the vWF (Von Willebrand Factor) has a central role in microthrombosis formation during COVID-19." (PMID 38786077, 2024). "vWF and other coagulation factors play a central role in platelet adhesion to damaged vascular subendothelium and clot formation, and their role in thrombosis in COVID-19 was recently shown." (PMID 38009950, 2024). "Furthermore, elevated levels of von Willebrand factor have been observed in the serum of patients with severe COVID-19." (PMID 39339853, 2024). "However, we found that vWF, citH3, and neutrophil count were only significant predictors of thrombosis in COVID-19 in our White population; however, these results need to be confirmed in a larger population since our sample size is small when divided by race." (PMID 39599792, 2024). "Although not firmly established, post-COVID complications apparently involve a persistent antigenic stimulus leading to what is commonly known as long-COVID and officially as post-acute sequelae of COVID-19 (PASC), arterial thrombosis, and microvascular thrombosis associated with activation of vWF." (PMID 39334765, 2024). "Notably, although high levels of the Von Willebrand Factor (VWF) in COVID-19 patients were already reported, our study indicates that the VWF is specifically elevated in early SARS-CoV-2 infection." (PMID 38672194, 2024). "vWF: vWF is involved in platelet adhesion and is elevated in COVID-19." (PMID 38996158, 2024). "IL-6 and SP-D are correlated with both BMI and age, while complement C5a, E-selectin, ICAM-1, MCP-1, Tie-2, and vWF levels were associated with age in patients with critical, but not severe COVID-19." (PMID 39507250, 2024). "In conclusion, COVID-19 may upregulate the vWF/FBLN5 signaling pathway in the patients with severe/critical symptoms, thereby increasing the likelihood of extracorporeal coagulation during hemodialysis in CKD patients." (PMID 38649864, 2024).
COVID-19 (continued). "Immunothrombosis biomarkers (specifically levels of tissue factor and vWF) could predict the development of ARDS in moderate-to-severe COVID-19." (PMID 39334765, 2024). "Notably, this study introduces the novel concept that elevated vWF levels play a crucial role in the COVID-19-induced hypercoagulability observed in CKD patients." (PMID 38649864, 2024). "In this study, we investigated the levels of neutrophil extracellular trap biomarkers and von Willebrand factor to assess if these could predict the occurrence of a thrombotic event in COVID-19 patients." (PMID 39599792, 2024). "Collectively, these results suggest that the vWF/FBLN5 pathway may play a pivotal role in the regulation of COVID-19-induced extracorporeal coagulation." (PMID 38649864, 2024). "Endothelial cell dysfunction in COVID-19 may result in increased vWF, platelet activation and hypercoagulability." (PMID 38732160, 2024). "The important role of VWF in the development of thrombosis in COVID-19 is confirmed by significantly more intense immunohistochemical (IHC) staining of VWF in the pulmonary vascular endothelium in patients with thrombotic complications than in patients without thrombotic complications." (PMID 39408067, 2024). "Generally, the proteome of EVs in COVID-19 shows abnormalities, such as complement activation and platelet hyperreactivity, and increased loads of vWF, UPAR, and ADAMTS13 that correlates with higher levels of the thrombotic marker, D-dimer, and increased disease severity." (PMID 38397093, 2024). "One hypothesis to explain the increased vWF levels in COVID-19 is the release of vWF from Weibel–Palade storage bodies after the virus’s entry into endothelial cells, mediating platelet aggregation and adhesion." (PMID 38732160, 2024). "In addition to disturbances in coagulation, enhanced platelet and von Willebrand factor (VWF) activation have been shown in COVID-19." (PMID 39237986, 2024). "In CKD patients, COVID-19 may exacerbate the vascular injury and induce a hypercoagulable state by upregulating vWF/FBLN-5." (PMID 38649864, 2024). "A deficiency in ADAMST-13 might be unable to counteract the VWF over-activity found after SARS-CoV-2 infection, long-COVID syndrome and, very rarely, COVID-19 vaccination." (PMID 38378550, 2024). "Indeed, lower ADAMS-13 levels have been described in COVID-19 patients where an elevated vWF:ADAMST-13 ratio strongly correlates with the severity of the disease and associates with endotheliopathy and immune dysfunction in long COVID syndrome." (PMID 38225643, 2024). "The vWF plays a crucial role in the coagulation cascade, especially in COVID-19 patients." (PMID 38649864, 2024). "In this pathological context, vWF, a key coagulation factor formed within endothelial cells and megakaryocytes, has been repeatedly reported elevated in the circulation of COVID-19 patients, where it acts as a marker of endotheliopathy and a predictor of poor outcome." (PMID 38225643, 2024). "Here, we observed ACE2 immunoreactivity in the vicinity of vWF+ endothelial cells in a small subset of vessels in the brainstem of COVID-19 patients indicating that ACE2 proteins are localized to vascular mural cells such as pericytes but not endothelial cells." (PMID 37875964, 2023). "Importantly, VWF-rich thrombi were exclusively found in patients with COVID-19 (39% vs 0%; P < .01), which is a key finding of this study." (PMID 37333991, 2023). "This, together with a relative decrease in VWF protease: ADAMTS-13 (A disintegrin and metalloproteinase with a thrombospondin type 1 motif, member 13) reported in COVID-19 patients, may result in larger VWF structures in circulation." (PMID 36634048, 2023). "Similarly, serum vWF levels in COVID-19 patients (n = 102) compared to healthy subjects (n = 26) is associated with severity and ICU admission (n = 17)." (PMID 36941580, 2023). "Nevertheless, both patients with COVID-19 who received steroids also had VWF+ thrombi." (PMID 37333991, 2023).
COVID-19 (continued). "In the pathological study, it was shown that COVID-19 increased von Wildebrand factor (vWF) levels, increased platelet accumulation via IL-6-related pathways, and as a result of all, fatty liver cells, increased liver cell damage and increased ALT levels were observed." (PMID 37374367, 2023). "However, the ADAMST13/vWF ratio tended to decrease in COVID-19 patients compared to healthy controls, negatively correlating with severity disease." (PMID 36941580, 2023). "Importantly, regulation of the VWF structure can also be affected in COVID-19, resulting in an abnormally high proportion of large-sized VWF multimers which display prothrombotic function." (PMID 36992384, 2023). "As a result, in patients with COVID-19, the secretion of vWF by the endothelium increases, which, together with other factors in severe forms of this disease, leads to thrombosis in the microvascular bed and ultimately to multiple organ failure and the death of the patient." (PMID 38132876, 2023). "We suggest including VWF diagnostics into coagulation analyses of patients with COVID-19, along with D-dimer levels and platelet counts, to deduce a more precise clinical prediction score for COVID-19 severity." (PMID 37333991, 2023). "Moreover, inflammatory markers including C-reactive protein, ferritin, interleukin (IL)-6, IP-10, MCP1, MIP1A, TNF-α, and vWF all were elevated in COVID-19 patients." (PMID 37854057, 2023). "In an attempt to determine whether genetic polymorphisms in the vWF and ADAMTS13 genes are associated with the progressive severity of COVID-19, χ2-tests were performed by comparing the genotype frequencies of each polymorphism in all patient cohorts." (PMID 36980889, 2023). "ET-1 as a marker of microvascular EC dysfunction showed a significant decrease in plasma concentrations with mean levels being in the normal range, while vWF:AG levels, representing endothelial damage, remained elevated in the majority of patients at 18 months after acute COVID-19." (PMID 36835948, 2023). "vWF is a highly thrombogenic protein, and dysregulation of the vFW-ADAMST-13 axis has been associated with the persistence of symptoms in subjects who have recovered from COVID-19." (PMID 38139298, 2023). "Although our study population focused on individuals who had recovered from COVID-19, our results showed that even after recovering from infection, vWF levels remained elevated in LC and LC-Mets groups compared to the individuals who did not develop sequelae from the disease (p < 0.0001)." (PMID 38139298, 2023). "Importantly, when levels of von Willebrand factor (VWF), P-selectin, and fibrinogen increase, with a normal or slightly increased D-dimer concentration, a rapid, aggressive COVID-19 progression must be acknowledged." (PMID 37873785, 2023). "Circulating nucleosome levels were strongly associated with higher vWF, but not with inflammatory cytokine levels, suggesting a role for NETs in endothelial injury or coagulopathy in the development of COVID-19 AKI." (PMID 37051234, 2023). "Severe COVID-19 patients (needed for mechanical ventilation, n = 19) showed the greatest increase in serum vWF levels and decreases in ADAMTS13 activity compared to moderate (needed for high flow oxygen therapy, n = 17) and mild (needed for low-flow oxygen therapy, n = 14) patients." (PMID 36941580, 2023). "Interestingly, the ratios of plasma VWF antigen to ADAMTS13 antigen were significantly higher in patients with severe or critical COVID-19 than in those with mild to moderate disease." (PMID 38002786, 2023). "Similarly, platelet-enriched characteristic NETosis thrombi were somewhat more frequent (28% vs 17%; P = .336), and VWF+ microthrombi tended to be more commonly seen in COVID-19 samples than in controls (35% vs 17%, respectively; P = .147)." (PMID 37333991, 2023).
COVID-19 (continued). "A hypercoagulable and hypofibrinolytic status has been described in patients 4 months after acute COVID-19, associated with persistent increased levels of D-dimer, factor VIII, plasminogen activator inhibitor-1 (PAI-1) and von Willebrand factor (vWF), markers of endothelial activation." (PMID 37626735, 2023). "•In COVID-19, von Willebrand factor (VWF) is highly elevated and predictive of adverse outcomes." (PMID 37333991, 2023). "Furthermore, COVID-19 patients have elevated levels of von Willebrand factor (VWF) antigen, VWF activity, and factor VIII, leukocytosis, thrombocytopenia, increased partial thromboplastin time, and low levels of antithrombin activity." (PMID 38002267, 2023). "COVID-19-infected patients have been shown to develop significantly more thrombotic complications and to have increased von Willebrand factor (VWF) activity, VWF antigen, and FVIII activity levels, as well as elevated D-dimer and fibrinogen levels, compared with non-COVID-19-infected patients." (PMID 36819387, 2023). "Interestingly, TLR2 signaling upregulates the release of vWF from Weibel–Palade bodies of endothelial cells, and from alpha granules in megakaryocytes/platelets vWF has a central role in microthrombosis formation during COVID-19." (PMID 36768817, 2023). "Forty-six percent of the patients with COVID-19 had VWF-rich thrombi, NETosis thrombi, or both." (PMID 37333991, 2023). "Additionally, levels of vWF:Ag were persistently high in 80% of COVID-19 survivors, reflecting endothelial cell damage and possibly attenuated endothelial function." (PMID 36835948, 2023). "In this case, recent experiments have demonstrated that antibodies against SARS-CoV-2 proteins recognize only some of the main autoantigens associated with COVID-19 coagulopathies, specifically the prothrombin component of aPS/PT, Factor VIII and von Willebrand Factor." (PMID 36769320, 2023). "NAC with COVID-19 may open up another new front here in that NAC can affect not only the oxidative stress aspect of COVID-19 but also the hypercoagulable state set by the excess of the vWF." (PMID 37534078, 2023). "Assessing coagulation factors to clinical markers of severity, we observed that in COVID-19 patients, vWF, XIII, VIII, and thrombomodulin levels correlated with lung function impairment (defined by SOFA respiratory score), whereas such correlation was not seen in the other sepsis cohorts." (PMID 36829233, 2023). "In patients affected by COVID-19, VWF is significantly increased and may suggest a tendency for thrombosis." (PMID 37240292, 2023). "Accentuated endothelial staining was found in controls, while VWF-rich thrombi were only found in patients with COVID-19 (11/28 [39%] vs 0/24 [0%], respectively; P < .01), as were NETosis thrombi enriched with VWF (7/28 [25%] vs 0/24 [0%], respectively; P < .01)." (PMID 37333991, 2023). "In addition, an imbalance between vWF and ADAMTS-13 i.e., elevated levels of vWF and decreased levels of ADAMTS13, has been shown to cause ARDS associated with COVID-19." (PMID 38069327, 2023). "Patients with COVID-19 exhibit a specific coagulopathy marked by heightened levels of fibrinogen, D-dimer fibrin degradation products, and significantly increased levels of VWF in the bloodstream." (PMID 38203218, 2023). "Similarly, circulating levels of endothelial markers such as ICAM-1, VCAM-1, and prothrombotic markers such as vWF or P-selectin have been reported in this cohort of COVID-19 ARDS patients." (PMID 37283766, 2023). "Several studies have reported a significant increase in circulating TF-expressing EVs that correlated with D-dimer levels, von Willebrand Factor, circulating leukocytes, and inflammatory markers, assuming the contribution of TF-EVs in disease determining severity and thrombosis in COVID-19 patients." (PMID 36768242, 2023).
COVID-19 (continued). "The functional information on platelets and vWF of critically ill COVID-19 patients may help to understand potential impairments in primary hemostasis contributing to the bleeding risk." (PMID 36611985, 2023). "NAC used as a supplement to the post-COVID-19 serum reduced the synthesis of vWF by 30%, p < 0.001." (PMID 38188630, 2023). "The release of vWf from Weibel–Palade bodies, which ensures rapid reaction to the damage and recruitment of inflammatory cells, further highlights endothelial activation in critically ill COVID-19 patients." (PMID 37175942, 2023). "Moreover, the markers of activation of the endothelial cells and platelets (i.e., vWF antigen and soluble P-selectin) were significantly increased in COVID-19 patients treated in the intensive care unit compared to those who did not require intensive care." (PMID 37092518, 2023). "We provide in situ evidence of VWF-rich thrombi, likely attributable to COVID-19, and suggest that VWF may be a therapeutic target in severe COVID-19." (PMID 37333991, 2023). "Similarly, while NETosis was not exclusive to COVID-19 samples in a subgroup of this cohort, characteristic NETosis thrombi enriched with VWF were exclusively found in patients with COVID-19 (25% vs 0%; P < .01)." (PMID 37333991, 2023). "Finally, a study performed on lung tissue of deceased COVID-19 patients (n = 9) also found increased tissue expression of vWF." (PMID 36941580, 2023). "Furthermore, reduced ADAMTS-13 levels and ultralarge VWF multimers have been observed in severe COVID-19." (PMID 36817284, 2023). "As the endothelial cell injury is a constant feature in the pathogenesis of COVID-19, Von Willebrand factor (VWF) and factor VIII (FVIII) excess, release and degree of elevation could be a good diagnostic and prognostic marker of the disease." (PMID 36138306, 2023). "Our results are highly consistent with the idea that acute respiratory distress syndrome and thrombotic complications of COVID-19 could be elucidated through VWF-related mechanism." (PMID 36138306, 2023). "The increased plasma levels of von Willebrand factor (VWF) in patients with COVID-19 was reported in many studies, and its correlation with disease severity and mortality suggest its important role in the pathogenesis of thrombosis in COVID-19." (PMID 35215805, 2022). "vWF multimers are relevant markers of endothelial damage, that have been hypothesised to drive micro-thrombosis in COVID-19 patients." (PMID 35189860, 2022). "Furthermore, high plasma levels of VWF antigen and pro-peptide are revealed in severe COVID-19 which they are indicative of endothelial stimulation as well as injury by secretion of VWF from Weibel-Plade bodies." (PMID 36128671, 2022). "It has recently been shown that thrombi in the pulmonary artery can develop in situ, a process, in which VWF could be involved in the COVID-19 setting." (PMID 36225927, 2022). "The morphological study of lungs in patients who died of COVID-19 using immunohistochemical staining for VWF may be helpful for a better understanding of the pathogenesis of thrombosis in this disease." (PMID 35215805, 2022). "Increased plasma VWF levels in patients with COVID-19 were observed in many studies, and their correlation with the disease severity and mortality suggests their important role in the pathogenesis of thrombosis in COVID-19." (PMID 35215805, 2022). "Elevated vWF in the plasma of COVID-19 patients has been discussed and could contribute to the clotting process." (PMID 35111367, 2022). "Endothelial stimulation and dysfunction are mediated by SARS-CoV-2 stimulation of the angiotensin-converting enzyme 2 receptor on the surface of endothelial cells and cytokine storm in COVID-19, resulting in the release of VWF and factor VIII from the endothelium." (PMID 35996516, 2022). "Notably, the increased vWF to ADAMTS13 ratio was accentuated in COVID-19 patients with a fatal outcome." (PMID 35242762, 2022).